VPS37B (VPS37B subunit of ESCRT-I)
Description:
Component of the ESCRT-I complex, a regulator of vesicular trafficking process. Required for the sorting of endocytic ubiquitinated cargos into multivesicular bodies. May be involved in cell growth and differentiation.
Synonyms: FLJ12750
Tractability: Antibody: UniProt places it where antibodies can reach, with high confidence; its Gene Ontology location is reachable by antibodies, with high confidence. PROTAC: ubiquitination databases record sites on it; its protein half-life has been measured.
Gene: Protein-coding gene on chromosome 12 (122,865,330 to 122,896,127, reverse strand). Ensembl gene ENSG00000139722.
Subcellular location: Late endosome membrane
Subcellular location (Human Protein Atlas): Cytosol; Primary cilium
Pathways (Reactome):
Disease: Budding and maturation of HIV virion; HCMV Late Events; Membrane binding and targetting of GAG proteins
Autophagy: Late endosomal microautophagy
Vesicle-mediated transport: Endosomal Sorting Complex Required For Transport (ESCRT)
Gene Ontology:
Molecular function: calcium-dependent protein binding; protein binding
Biological process: positive regulation of viral budding via host ESCRT complex; viral release from host cell; macroautophagy; membrane fission; multivesicular body assembly; protein targeting to membrane; protein targeting to vacuole; protein transport to vacuole involved in ubiquitin-dependent protein catabolic process via the multivesicular body sorting pathway; ubiquitin-dependent protein catabolic process via the multivesicular body sorting pathway; viral budding via host ESCRT complex
Cellular component: cytoplasm; endosome; endosome membrane; ESCRT I complex; extracellular exosome; midbody; plasma membrane; late endosome membrane
Genetic constraint (gnomAD): Loss-of-function variants: 11 observed, 21.45 expected, observed/expected ratio (o/e) 0.51, 90% interval 0.32 to 0.85. The upper end of that interval is the gene's LOEUF score, 0.85, which puts it in group 3 of 6, group 1 being the genes least tolerant of losing a copy. Missense variants: 387 observed, 360.83 expected, observed/expected ratio (o/e) 1.07, 90% interval 0.99 to 1.17. Synonymous variants: 167 observed, 150.02 expected, observed/expected ratio (o/e) 1.11, 90% interval 0.98 to 1.27.
Homologues: Orthologues: chimpanzee VPS37B (99% identical), macaque VPS37B (98% identical), pig VPS37B (93% identical), dog VPS37B (91% identical), guinea pig VPS37B (88% identical), mouse Vps37b (84% identical), rabbit VPS37B (78% identical), rat Vps37b (62% identical), tropical clawed frog vps37b (60% identical), zebrafish vps37ba (52% identical), zebrafish vps37bb (40% identical), Drosophila melanogaster Vps37B (21% identical). Paralogues in human: VPS37C (40% identical), VPS37D (29% identical), VPS37A (18% identical).
Diseases named in the same sentence as VPS37B in open-access papers:
VPS37B is named in the same sentence as 8 diseases in open-access papers, as found by Europe PMC text mining. Sharing a sentence is not in itself a finding about the gene and the disease. The quoted sentences say what the papers report.
colorectal cancer (2 papers, 2023 to 2025). A primary or metastatic malignant neoplasm that affects the colon or rectum. "Accordingly, recent studies have shown that expression of VPS37B is decreased in advanced colorectal cancer." (PMID 37439191, 2023). "Other studies have shown that VPS37B silencing in DLD1 cells, a human colorectal cancer cell line, destabilizes the entire ESCRT-I complex, thereby disrupting endosomal trafficking." (PMID 40699655, 2025).
COVID-19 (1 paper, 2022). A disease caused by infection with severe acute respiratory syndrome coronavirus 2. "Here, four hub genes including MVB12A, CHMP6, STAM, and VPS37B were considered to be involved in the core regulation of autophagy in severe COVID-19 cases." (PMID 35923698, 2022). "Therefore, MVB12A, CHMP6, STAM, and VPS37B were regarded as hub genes regulating autophagy in severe COVID-19." (PMID 35923698, 2022).
viral infections (1 paper, 2025). "Like CHMP4C, VPS37B has been studied in the context of viral infections." (PMID 40699655, 2025).
tumor (2 papers, 2024 to 2025). "We observed that activated NK cells in VPS37B high expression group were significantly decreased, suggesting that high expression level of VPS37B may be related to the decrease in the number of NK cells as well as dysfunction, resulting in tumor recurrence and metastasis." (PMID 39668817, 2024). "Evaluation using StromalScore, ImmuneScore, and EstimateScore indicated that most ESCRT genes, such as VPS37D in DLBC and VPS37B in GBM, exhibited a significant negative correlation with tumor immune infiltration." (PMID 40230849, 2025).
cancer (1 paper, 2025). A tumor composed of atypical neoplastic, often pleomorphic cells that invade other tissues. "Some genes exhibited positive regulation in particular cancer types, including VPS37C in DLBC and CHMP3 and VPS37B in TGCT, which were positively correlated with immune cell enrichment." (PMID 40230849, 2025).
VPS37B also shares sentences with these, for which no sentence is quoted: Alzheimer disease (1 paper); glioma (1); infection (1).